MIR4790 (microRNA 4790)
Synonyms: hsa-mir-4790
Gene: MicroRNA gene on chromosome 3 (5,250,177 to 5,250,255, reverse strand). Ensembl gene ENSG00000265180.
Homologues: Orthologues: chimpanzee MIR4790 (100% identical), macaque MIR4790 (100% identical).